CD33 (CD33 molecule)
Diseases named in the same sentence as CD33 in open-access papers (continued):
Sharing a sentence is not in itself a finding about the gene and the disease.
Alzheimer disease (continued). "CD33 may be activated continuously by sialic-acid-containing glycoproteins and glycolipids, which are structural elements of amyloid plaques in the brains of Alzheimer’s disease patients, resulting in an inhibition of microglia-mediated immune activation." (PMID 35408990, 2022). "The biased nature of the inhibitory effect of CD33 on receptors coupled to DAP10 or SAP adaptor proteins described here provides new insights that could help to study the role of CD33 in diseases such as Alzheimer's disease." (PMID 31143782, 2019). "For example, several genes causing ALS and/or frontotemporal dementia (C9orf72, VCP, SQSTM1, OPTN, UBQLN2, GRN, CHMP2B) affect the autophagic machinery; and some Alzheimer’s Disease genes (APOE, TREM2, CD33, ABCA7) are preferentially or exclusively expressed in microglia." (PMID 33892821, 2021). "Four drugs could be used synergistically to reduce microglia-mediated inflammation in Alzheimer’s disease, through the inhibition of CSF1R and CD33." (PMID 32398742, 2020). "Although the present study did not include a direct Alzheimer’s disease cohort, the mechanisms we observed in viral hepatitis may parallel CD33’s role in the former condition, particularly in relation to neuroinflammation." (PMID 40637125, 2025).
myelodysplastic syndrome (42 papers, 2017 to 2025). A clonal hematopoietic disorder characterized by dysplasia and ineffective hematopoiesis in one or more of the hematopoietic cell lines. "One report describes an infant with low levels of surface CD33 expression, copper deficiency, and myelodysplastic syndrome." (PMID 40043053, 2025). "CD16 × IL-15 × CD33 TriKE is being evaluated in phase I and II clinical trials in patients with advanced systemic mastocytosis, relapsed or refractory AML, or CD33-expressing high-risk myelodysplastic syndromes NCT03214666." (PMID 33505304, 2020). "Other NKCEs under assessment in haematological malignancies included a TriKE (GTB-3550) targeting CD16, IL-15, and the tumour-associated antigen CD33 in AML and high-risk myelodysplastic syndromes in a phase 1 trial (NCT03214666)." (PMID 38223411, 2024). "Transcriptome analysis in CD33+BM blast cells purified from a patient with AML transformed from myelodysplastic syndrome showed that the expression of SPINK2 was higher than control CD33+ BM cells." (PMID 37359898, 2023). "The inhibitory function of CD33 induced by S100A9 in the context of myelodysplastic syndromes has been demonstrated by several studies." (PMID 37056775, 2023). "A CD16xCD33 bispecific engager and TriKE targeting CD16, CD33, and stimulating IL15 improve NK cell killing of CD33+ myelodysplastic syndrome cells." (PMID 35669776, 2022). "Two studies are focused in AML/Myelodysplastic Syndromes and target CD33 or utilized NKG2D CAR-NK cells, while one study targets BCMA in MM and other CD7 in T-cell malignancies." (PMID 35493522, 2022). "Because of this expression pattern, CD33-directed therapies are used in malignancies such as chronic myelomonocytic leukemia, myelodysplastic syndrome, and acute lymphoblastic leukemia." (PMID 32873829, 2020). "Treatment with CD16 × CD33 BiKE enhances degranulation and tumor necrosis factor (TNF)-α, and interferon (IFN)-γ production against CD33+ myelodysplastic syndrome targets and reverses immunosuppression of NK cells by myeloid-derived suppressive cells." (PMID 33299651, 2020). "In myelodysplastic syndrome, BI 836858, which is a Fc-engineered monoclonal antibody against CD33, also reduce MDSCs by antibody-dependent cellular cytotoxicity and block CD33 downstream signaling, thereby preventing immunosuppressive cytokine secretion." (PMID 30792719, 2019). "CD33 is also expressed in myelodysplastic syndrome and chronic myelomonocytic leukemia An ongoing trial targeting CD33 expressing myeloid-derived suppressor cells using the same antibody described in this article is ongoing." (PMID 29515764, 2018). "It is unclear if the pathologies were directly related to CD33 and if the loss of CD33 expression was due to the dysmyelopoiesis present in myelodysplastic syndrome or germline CD33 variants carried by the infant as no DNA sequencing was reported." (PMID 40043053, 2025). "Furthermore, in the bone marrow, the heterodimer also contributes to development of myelodysplastic syndrome (MDS) (a B cell malignancy) by interacting with CD33." (PMID 29762501, 2018). "The efficacy of CD33/CD16 BiKE to induce NK cell function in myelodysplastic syndrome (MDS) cases showed significant NK cell degranulation and IFNγ and TNFα production in MDS patients." (PMID 34827170, 2021). "A trifunctional molecule combining IL-15 with CD16 and CD33 engagers has also been constructed to support NK cell response in myelodysplastic syndrome (MDS)." (PMID 32272610, 2020). "In vivo, treatment with the CD16xCD33 BiKE successfully reversed myeloid-derived suppressor cells’ (MDSCs) immunosuppression of NK cells and induced killing of CD33+ MDSCs and CD33+ myelodysplastic syndrome (MDS) targets." (PMID 32013092, 2020). "CD33, a defining marker of MDSCs (CD33+HLA-DR−Lin−), is highly expressed in myelodysplastic syndrome (MDS) MDSCs." (PMID 32005273, 2020).
myelodysplastic syndrome (continued). "For example, an Anti-CD16 × CD33 bispecific antibody for the treatment of myelodysplastic syndrome (MDS) has been reported to eradicate CD33+ MDS cells and targeted CD33+ myeloid-derived suppressor cells resulting in reduced immunosuppression in the TME and enhanced antitumor efficacy." (PMID 40741595, 2025). "A CD16xCD33 bispecific engager and TriKE targeting CD16, CD33 and stimulating IL15 improved NK cell killing of CD33+ myelodysplastic syndrome cells." (PMID 35185932, 2022). "For example, engagers targeting NK cells to CD30+ lymphomas, CD33+ myelodysplastic syndrome, CD133+ colon cancer, CLEC12A+ and CD33+ AML are all in clinical development." (PMID 35185932, 2022). "For instance, engagers targeting NK cells for CD30+ lymphoma, CD133+ colon cancer, CD33+ myelodysplastic syndrome, CLEC12A+ and CD33+ acute myeloid cell (AML) are all in clinical development." (PMID 35669776, 2022). "In patients with myelodysplastic syndrome (MDS), host NK cells were activated in the presence of CD16 × CD33 BiKEs to target CD33+ MDS cells." (PMID 34071099, 2021). "Anti-CD16/CD33 BiKEs showed promise in an in vitro study treating myelodysplastic syndrome (MDS)." (PMID 31544834, 2019). "Similarly, in human cancers, anti-CD33 therapies like AMV564, a tetravalent bispecific antibody targeting CD33/CD3, have been used to reduce MDSCs and enhance T cell function in patients with myelodysplastic syndromes." (PMID 40050933, 2025). "Previous studies have shown that NK-cell-mediated cytotoxicity could occur by CD16 × CD33 (1633) BiKEs that ligated CD16 on NK cells and CD33 on tumor cells, including myelodysplastic syndromes (MDS) and AML." (PMID 31027331, 2019). "GTB-3550 TriKE which is a primal construct with CD16 scFv and targets on CD33+ AML and myelodysplastic syndromes (MDS) is the first TriKE in phase I clinical trials (NCT03214666)." (PMID 38745768, 2024).
breast carcinoma (34 papers, 2011 to 2025). "The number of tumor-infiltrating CD33-positive MDSCs is associated with aldehyde dehydrogenase (ALDH)-positive CSCs in breast cancer patients." (PMID 32726950, 2020). "Patients with breast cancer displayed elevated levels of CD33+CD15− M‐MDSCs compared with healthy controls." (PMID 39749673, 2025). "Previous reports revealed that the NF‐κB signalling pathway plays a crucial role in the amplification and maintenance of the immunosuppression function of CD33+ MDSCs in breast cancer." (PMID 37965796, 2023). "eMDSCs are a newly defined subset of MDSCs, whose phenotype in breast cancer were defined as Lin−HLA-DR-CD45+CD33+CD13+CD14−CD15− in humans and CD11b+Gr-1-F4/80-MHC-II- in mice." (PMID 36329699, 2022). "Breast cancer samples were separated into two groups based on the median number of CD33+ eMDSCs infiltrated locally: lowly infiltrated eMDSCs (eMDSCslow, n = 7) and highly infiltrated eMDSCs (eMDSCshigh, n = 7)." (PMID 36329699, 2022). "Since 2013, we have focused on CD33+ eMDSCs in human breast cancer tissues, and found they possess potent suppression on T cells proliferation and cytokine production." (PMID 36329699, 2022). "Multispectral IF staining was performed to detect the expression of CD33 protein in 280 primary breast cancer patients from two cohorts." (PMID 36329699, 2022). "According to the median number of CD33+ eMDSCs that infiltrated locally, breast cancer patients were categorized into eMDSCshigh and eMDSCslow groups." (PMID 36329699, 2022). "Cancer cell-derived IL-6 activates the STAT3 pathway in MDSCs, subsequently upregulating indoleamine 2,3-dioxygenase in co-cultures of human CD33(+) myeloid progenitors with MDA-MB-231 breast cancer cells." (PMID 32726950, 2020). "Lin− HLA-DR− CD33+ CD11b+ MDSCs were isolated from the blood of patients with glioblastoma, breast cancer, colon cancer, lung cancer and kidney cancer." (PMID 31379854, 2019). "In our previous study, we identified a subset of immature MDSCs in human breast cancer tissues with the phenotype of Lin−HLA−DR−CD45+CD33+CD13+CD14−CD15− that exerted potent immunosuppressive effects on T cells in vitro and in vivo." (PMID 30083161, 2018). "We next co-cultured peripheral blood immature myeloid cells (CD33+CD34+CD15+) from healthy blood donors with the human breast cancer cell line MDA-MB231." (PMID 29973593, 2018). "In our previous study, we identified a subset of poorly differentiated eMDSCs in breast cancer that expressed an immature phenotype of Lin−HLA-DR−CD45+CD33+CD13+CD14−CD15− and displayed potent suppression of T cells in vitro and in vivo." (PMID 29326716, 2017). "We found a significant expansion of CD33+CD11b+HLA-DR−/low myeloid cells in the TME of breast cancer patients." (PMID 28283696, 2017). "We observed a cluster of CD33+CD13+CD14−CD15− cells in breast cancer tissue, which represented the predominant phenotype of MDSCs in breast cancer." (PMID 29326716, 2017). "Twenty fresh breast cancer tissue samples were collected to study the correlation between RNA levels of tumor-derived IL-6 and percentages of CD45+CD33+CD13+CD14−CD15− MDSCs in breast cancer tissues by flow cytometry analysis." (PMID 29326716, 2017). "According to the number of CD33+ MDSCs that infiltrated locally, breast cancer patients were divided into lowly infiltrated MDSC group (MDSCslow) and highly infiltrated MDSC group (MDSCshigh)." (PMID 29326716, 2017). "In tumor sections from 30 breast cancer patients, the percentage of CD33+/pSTAT3+ co-expressing cells was 80, suggesting a critical role for this pathway in driving IDO expression in MDSCs associated with primary human breast tumors." (PMID 27148255, 2016). "G-MDSCs express a granulocytic marker CD15 or CD66b in addition to CD11b and CD33 in head and neck cancer, non-small cell lung cancer, pancreas cancer, bladder cancer, renal cell cancer, and breast cancer." (PMID 26078490, 2015).
breast carcinoma (continued). "In Myeloid cell group, HLA DR on CD33-HLA DR+(P = 0.043, OR = 0.979, 95%CI = 0.960~0.999) had a negative causal relationship with breast cancer." (PMID 39418291, 2024). "Similarly, an escalation in lymph node metastases among breast cancer patients correlated with an increase in indoleamine 2,3-dioxygenase (IDO)-expressing CD45+CD33+CD14−CD15− MDSCs within breast cancer tissue." (PMID 38361941, 2024). "In breast cancer tissues, many reports have described, with various degree of accuracy, myeloid cells exhibiting an immature phenotype (CD33+CD13+CD14-CD15-) and immunosuppressive properties, which have been associated with adverse prognostic features (higher tumor grade, positive lymph nodes)." (PMID 35309358, 2022). "In the present work, we observed a significant positive correlation between CD33+ MDSCs and PD-1−PD-L1+ Bregs, and the level of MDSCs was an independent prognostic factor and might be a promising biomarker for evaluating breast cancer patient prognosis." (PMID 33967272, 2021). "The potential correlation between Mo-MDSCs and CTCs was hitherto unexplored in breast cancer patients, although it has been proposed that MDSCs (CD11b+CD33+Lin−HLA-DR− cells) may correlate with CTCs." (PMID 31925475, 2020). "CD33+ MDSCs were scattered in the stroma of breast cancer tissues with varying sizes and shapes." (PMID 29326716, 2017). "Therefore, we defined the phenotype of CD45+CD13+CD33+CD14−CD15− to precisely distinguish breast cancer MDSCs." (PMID 29326716, 2017). "Another study showed an expansion of CD33+HLA-DR−/lowCD15+CD11b+ MDSC in peripheral blood of breast cancer patients with high psychological stress compared to those with lower stress levels, thereby suggesting an association between stress and immune function in breast cancer patients." (PMID 28283696, 2017). "Revisiting previously published gene expression data for this group of breast cancer cell lines, which lack CD33+ MDSC induction, we identified FLT3L and TGFβ as differentially expressed candidates for CD11b+ MDSC subset induction from our panel of putative MDSC-inducing factors." (PMID 21658270, 2011). "Patients with breast cancer exhibited lower CD3+CD4+ T lymphocyte, CD3+CD8+ CTL, and CD33+CD15− M‐MDSC levels compared with healthy controls." (PMID 39749673, 2025). "Patients with breast cancer exhibited reduced CD3+CD4+ T lymphocyte, CD3+CD8+ CTL, and CD33+CD15− M‐MDSC levels compared with healthy controls." (PMID 39749673, 2025). "Levels of CD33+CD15−, an M‐MDSC subtype, were decreased in the breast cancer group (p = 0.002)." (PMID 39749673, 2025). "CAR-NK-92 cells based on CD28-CD3ζ signaling domain have anti-tumor cytotoxicity targeting EpCAM and ErB2 breast cancer cells, EGFR on glioblastoma cells and breast cancer brain metastases, CD19 on B-cell malignancies, CS1 on multiple myeloma cells, and CD33 on acute myeloid leukemia cells." (PMID 39633491, 2024). "To further elucidate whether miR-145-3p contributed to metastasis and angiogenesis of breast cancer, we evaluated the expression levels of VEGFA and CD33 by IHC." (PMID 34350110, 2021). "A consistent phenomenon was observed in human breast cancer in which the sustained activation of the JAK/STAT signaling pathway dominated the amplification and immunosuppressive capacity of the Lin−HLA-DR−CD45+CD13+CD33+CD14−CD15− e-MDSCs." (PMID 30083161, 2018). "Clinically, breast cancer patients possess sCLU expression only in mature CD68+ macrophages but not in immature CD33+ immunosuppressive myeloid cells infiltrating the tumors." (PMID 27405665, 2016). "Using CD33 and CD68 as markers for MDSCs and mature macrophages respectively, we analyzed whether they infiltrate human breast cancer tissues and which population expresses sCLU." (PMID 27405665, 2016).
breast carcinoma (continued). "Our observation of selective expression of sCLU in infiltrating CD68+ macrophages but not in CD33+ immature myeloid cells within breast cancer tissues is an important new finding that explains the immune-restorative capacity of certain anti-cancer drugs." (PMID 27405665, 2016). "Interestingly, no human breast cancer cell line (0/9) tested generated CD33+ MDSC from PBMC after a one-week co-culture." (PMID 21658270, 2011). "Human MDSC were isolated by magnetic bead column separation after one-week co-culture with SCCL-MT1 or USC-HN2 HNSCC cell lines (CD33+) or MCF-7 breast cancer cell line (CD11b+) and non-suppressive CD33+ or CD11b+ control cells were isolated from medium only PBMC cultures." (PMID 21658270, 2011). "CD33+ MDSC could be induced by cancer cell lines from all tumor types with the notable exception of those derived from breast cancer (0/9, regardless of hormone and HER2 status)." (PMID 21658270, 2011). "CD33+ MDSC could be generated by at least one cell line of every human tumor type examined (cervical/endometrial, ovarian, pancreatic, lung, head and neck, renal cell, liver, colorectal, prostate, thyroid, gastric, bladder, sarcoma, and glioblastoma), with the exception of breast carcinoma." (PMID 21658270, 2011).